RN7SL820P (RNA, 7SL, cytoplasmic 820, pseudogene)
Gene: Miscellaneous RNA gene on chromosome 2 (196,289,409 to 196,289,707, forward strand). Ensembl gene ENSG00000276200.
Homologues: Orthologues: chimpanzee Metazoa_SRP (99% identical), macaque Metazoa_SRP (95% identical). Paralogues in human: RN7SL2 (83% identical), RN7SL1 (82% identical), RN7SL88P (81% identical), RN7SL126P (81% identical), RN7SL269P (81% identical), RN7SL3 (81% identical), RN7SL507P (81% identical), RN7SL448P (80% identical), RN7SL481P (80% identical), RN7SL451P (80% identical), RN7SL45P (80% identical), RN7SL828P (80% identical), and 701 more.